CCNA1 (cyclin A1)
Diseases named in the same sentence as CCNA1 in open-access papers (continued):
Sharing a sentence is not in itself a finding about the gene and the disease.
cervical cancer (continued). "As shown in this study, HK2 overexpression could activate ERK1/2 through the Raf/MEK/ERK signaling pathway, further promoting cell proliferation and tumor formation by inducing cyclin A1 and reducing p27 expression in cervical cancer cells." (PMID 33324557, 2020). "MiR-372 suppresses the growth of cervical cancer cells by downregulating cyclin A1 and CDK2." (PMID 26673619, 2016). "Cervical cancer and normal cervix tissue was used to select the top 5 discriminating loci among 27 loci in 4 genes (CCNA1, CADM1, DAPK1, JAM3), and one locus of JAM3 (region M4) was identified and confirmed with 267 and 224 cervical scrapings from 2 independent colposcopy referral studies." (PMID 26517242, 2015). "Promoter methylation of the tumor suppressor gene Cyclin A1 could be associated with Human Papillomavirus 16 (HPV16) induced Head and Neck Squamous Cell Carcinoma (HNSCC) and Cervical Carcinoma." (PMID 22712549, 2012). "Therefore, it was interesting to explore whether there had a potential HK2-ERK-cyclin A1/p27 signaling cascade on regulating cell proliferation and tumor formation in cervical cancer." (PMID 33324557, 2020). "Therefore, the anti-oncogenic role of miR-372 in endometrial carcinoma may be similar to its role in cervical carcinoma through the downregulation of Cyclin A1 and CDK2 expression." (PMID 26673619, 2016). "All of the cervical cancer cells subjected to EGF treatment expressed more p-ERK1/2, cyclin A1, and c-myc and less p27 (p<0.05), and grew much more quickly (p<0.05)." (PMID 33324557, 2020). "All of the cervical cancer cells subjected to FR180204 treatment grew much more slowly (p<0.05) and expressed less ERK1/2, p-ERK1/2, cyclin A1, and c-myc and more p27 (p<0.05)." (PMID 33324557, 2020). "LINE-1, HS3ST2, CCNA1, EPB41L3, EDNRB, LMX1, and DPYS were hypermethylated in cervical cancer tissues, CIN III and CIN II, versus normal tissues and CIN I, of which EPB41L3 seems to be the best marker." (PMID 29850477, 2018). "Some studies reported that the CCNA1 methylation was found in high grade lesions and cervical cancer but no CCNA1 promoter methylation in normal cervixes." (PMID 32102526, 2020). "Furthermore, compared to HSILs, CCNA1 and TFPI2 are the most prominently methylated genes in cervical cancers." (PMID 32559232, 2020). "CCNA1 could be a methylation marker to distinguish normal lesion from high-grade lesion while CCNA1, hTERT1, hTERT2 and TWIST1 could distinguish cervical cancer from normal and precancerous stage." (PMID 27933097, 2016). "Similar results were also observed in cervical cancer, in which miR-372 was expressed at low levels and may downregulate CDK2 and cyclin A1 to control cell growth and cell cycle progression." (PMID 25880458, 2015). "This also showed that the known cervical cancer-specific markers are not enriched to the same extend (CCNA1 is highest at position 234), implying the existence of better hypermethylated markers, involved in cervical cancer, in the TOP3000 list." (PMID 19025626, 2008). "However, data about CCNA1 promoter methylation test in self-sampled cervical cancer screening method are not available." (PMID 33112548, 2020).
leukemia (13 papers, 2013 to 2024). A malignant (clonal) hematologic disorder, involving hematopoietic stem cells and characterized by the presence of primitive or atypical myeloid or lymphoid cells in the bone marrow and the blood. "DBF activates the expression of genes encoding the proteins involved in leukemia cell survival, such as KIT, CTNNB1, CCNE1, NFKB1, E2F1, and downregulates the expression of CCND2, CCNA1, and FLT3 genes." (PMID 34564151, 2021). "CCNA1 is involved in cell cycle progression and its silencing in leukaemia cells inhibits cell growth." (PMID 34290392, 2021). "This indicated that cyclin A1 can contribute to the induction of a leukemic phenotype but that at least other cooperative events were necessary to induce a cyclin A1-triggered leukemia." (PMID 26080083, 2015). "Transcription corepressor CTBP2 has been reported to directly bind acinus, which is regulated by NGF (nerve growth factor), inhibiting its stimulatory effect on cyclin A1 expression in leukemia." (PMID 25628645, 2014). "In contrast to its low expression in the majority of normal tissues, elevated level of cyclin A1 is frequently observed in various types of cancers including prostate cancer, leukemia, testicular cancer, ovarian cancer and lung cancer." (PMID 23991063, 2013). "These previous findings demonstrate that abnormal expression of cyclin A1 results in the development of leukemia and progression of prostate cancer." (PMID 23991063, 2013). "Similarly, PRAME previously elicited a robust immune response in leukemia and melanoma, and CCNA1 was adopted as a vaccine target for acute myeloid leukemia." (PMID 39136024, 2024). "Importantly, treatment with DBF causes significant reduction of CCNA1 and CCND2 expression (genes, encoding key regulators of cell cycle transition cyclin A1 and cyclin D2 proteins) in most of the studied leukemia cells." (PMID 34564151, 2021). "Cyclin A2, which is ubiquitously expressed in dividing cells and plays role in DNA replication, entry into mitosis and spindle assembly, and cyclin A1, whose function is less clear and which is expressed in spermatocytes, leukemia cells and in postmitotic multiciliated cells." (PMID 32366979, 2020). "Most importantly, no Cyclin A1-derived peptides were identified on benign tissue samples proving the tumor/leukemia-exclusivity of this antigen even on HLA ligandome level." (PMID 32157447, 2020). "SRPK2 promoted the cell proliferation of leukemia by regulating cyclin A1 (not cyclin A2) expression." (PMID 31898732, 2020). "While several leukemia-associated antigens (LAA) have been identified (such as WT1, Cyclin A1), leukemia specific antigens (LSA) have not been as well defined." (PMID 31291378, 2019). "In leukemia cells, SRPK2 overexpression leads to hyperphosphorylation of the splicing factor acinus, which in turn is responsible for increasing the transcription level of cyclin A1 and affecting cell proliferation." (PMID 26244849, 2015).
prostate carcinoma (12 papers, 2009 to 2025). A carcinoma that arises from epithelial cells of the prostate gland. "CCNA1 is frequently inactivated in UCC, which indicates its anti-proliferative activity; however, in a recent study, it has been implicated that CCNA1 contributes to prostate cancer invasion and metastasis." (PMID 24980822, 2014). "In patients, high expression levels of cyclin A1 and aromatase proteins in metastatic bone lesions support the notion that stem cell-like prostate cancer cells overexpressing cyclin A1 and aromatase, preferentially metastasize to bone." (PMID 36258057, 2022). "In prostate cancer, the expression of Cyclin A1 has been shown to be enhanced in metastatic lesions compared to the primary tumor, while its over-expression in stem-like cells fostered bone marrow homing and metastatic growth." (PMID 36230567, 2022). "IRE1α has also been shown to enhance prostate cancer cell proliferation through inducing cyclin A1 expression." (PMID 34295814, 2021). "PI3K/Akt or MAPK/ERK signal activation triggered by IL-6 has been reported to induce cancer cell proliferation through the upregulation of cyclin A1 in hepatoma, prostate cancer, and multiple myeloma." (PMID 30927911, 2019). "Cyclin A1 is able to mediate the effect of PI3K/AKT to promote survival of prostate cancer cells in the presence of high level of cytokine, interleukin-6." (PMID 23991063, 2013). "We have previously shown that altered cyclin A1 expression promotes prostate cancer metastasis by inducing the expression and activities of MMPs in prostate cancer cells." (PMID 23991063, 2013). "The functional consequences of cyclin A1 overexpression have been elucidated in leukemic and prostate cancer cell lines and mouse models." (PMID 23991063, 2013). "We have previously shown that tumors from patients with advanced prostate cancer and distant metastases exhibited high level of cyclin A1 expression." (PMID 23991063, 2013). "In this way, IL-6 could trigger the PI3K/Akt, NF-κB and MAPK/ERK signaling pathways in a manner similar to that observed in other tumors such as prostate cancer with the upregulation of cyclin A1, or bladder cancer and multiple myeloma." (PMID 29930760, 2018). "Moreover, cyclin A1 promotes invasion and metastasis of prostate cancer cells by increasing the expression of VEGF and matrix metalloproteinases (MMPs)." (PMID 23991063, 2013). "The mRNA sequencing analysis also reveals that several genes, such as NUDT11, CCNA1, and HNF1B, known to promote prostate cancer progression, are significantly up-regulated in the CIC knock-down PC-3 cells." (PMID 26124181, 2015). "The transcriptional and post-transcriptional regulation of cyclin A1 by Roscovitine was confirmed in a panel of NSCLC (A549 and H23), breast (MCF-7 and MDA-MB-231) and prostate cancer (LNCAP and DU145) cell lines (data not shown)." (PMID 20684776, 2010).
ovarian carcinoma (10 papers, 2015 to 2025). A malignant neoplasm originating from the surface ovarian epithelium. "Elevated expression of CCNA1 has been strongly associated with resistance to paclitaxel, doxorubicin and 5-fluorouracil in human ovarian cancer cells." (PMID 41415563, 2025). "An augmented expression of the Cyclin A1 gene has been associated with cellular resistance to paclitaxel, doxorubicin, and 5-fluorouracil in ovarian cancer." (PMID 36230567, 2022). "For example, CCNA1/cyclin A1 has recently been suggested as a potential diagnostic marker in papillary thyroid carcinoma and is a chemoresistance-associated biomarker in ovarian cancer." (PMID 38447798, 2024). "Consistently, in this study, exogenously expressed of HK2 also promoted cell growth in human ovarian cancer cells by accelerating cell cycle progression (up-regulated the expression of cell cycle-related factors, like cyclin A1, cyclin D1 and cyclin E1)." (PMID 35953860, 2022). "It has been reported that the expression of cyclin A1 was sufficient to enhance paclitaxel resistance, whereas the siRNA-induced decrease in cyclin A1 expression in the ovarian carcinoma cell line sensitized cells to paclitaxel cytotoxicity." (PMID 35256739, 2022). "Although not as important as the other A-type cyclin (cyclin A2/cyclin A), cyclin A1 also is involved with the development of taxane resistance in ovarian cancer." (PMID 33182737, 2020). "Few studies have shown that increased CCNA1 expression is seen in high-grade epithelial ovarian cancers." (PMID 33182737, 2020). "Cyclin A1 is a promising antigen for T cell therapy being selectively expressed in high-grade ovarian cancer (OC) and acute myeloid leukemia (AML) stem cells." (PMID 32157447, 2020). "Cyclin A1 expression has been reported in several epithelial malignancies, including testicular, endometrial, and epithelial ovarian cancer (EOC)." (PMID 26499264, 2015). "In the larger set of ovarian cancer samples, we detected Cyclin A1 staining in all the samples, with at least moderate staining in half of the samples irrespective of the histological grade." (PMID 26499264, 2015). "Cyclin A1 appears to be a highly suitable antigen in patients with EOC for targeted T-cell therapy because of its selectively high expression in the vast majority of high-grade ovarian cancers irrespective of clinical stage." (PMID 26499264, 2015).
acute myeloid leukemia (9 papers, 2011 to 2024). Acute myeloid leukemia (AML) is a group of neoplasms arising from precursor cells committed to the myeloid cell-line differentiation. "In acute myeloid leukemia patients, high expression of Cyclin A1 mRNA was associated with increased survival." (PMID 25068292, 2014). "We recently described Cyclin A1 as a T-cell antigen with aberrant expression in the stem cell compartment of acute myeloid leukemia." (PMID 26499264, 2015). "Cyclin A1 is highly expressed in testis and acute myeloid leukemia where it is involved in male meiosis and cell cycle regulation at the restriction points G1/S and G2/M." (PMID 24019929, 2013). "Cyclin A1 is highly expressed in Acute Myeloid Leukemia (AML) and cyclinA1 overexpression can induce leukemia." (PMID 21750715, 2011). "c-myc was reported to transactivate the cyclin A1 promoter and may be responsible for the elevated expression of cyclin A1 in acute myeloid leukaemia." (PMID 23941782, 2013). "Cyclin A1 (CCNA1), a cell cycle regulatory protein, was initially identified as a compound essential for spermatogenesis and acute myeloid leukemia development." (PMID 37612452, 2023). "The highly selective expression pattern has not only been shown at the mRNA and protein level, but also by ligandome analysis, demonstrating that Cyclin A1 peptides bind to MHC class I in acute myeloid leukemia cells but not in healthy tissues or during normal hematopoiesis." (PMID 26499264, 2015).
gastric cancer (7 papers, 2014 to 2023). A primary or metastatic malignant neoplasm involving the stomach. "The radiation-mediated reduction in KDM4B inhibited CCNA1 expression under hypoxia condition, which severely impeded gastric cancer cell proliferation." (PMID 35186950, 2021). "A strong reduction in the expression of PGP9.5, NMDAR2B, and CCNA1 was observed in primary gastric cancer tissues when the promoter DNA methylation was super-high." (PMID 26447864, 2015). "Hypoxia upregulates KDM4B expression, which demethylates H3K9 at Cyclin A1 promoter, stimulating gastric cancer cell proliferation." (PMID 24858415, 2014). "In addition, KDM4B mediates gastric cancer cells proliferation under hypoxia by stimulating cyclin A1 gene expression." (PMID 24858415, 2014). "In gastric cancer cells, KDM4B binds to the promoter CCNA1 to result in CCNA1 upregulation under hypoxic conditions, thereby promoting cancer cell proliferation." (PMID 35186950, 2021). "Additionally, another study showed that the levels of Bcl-2, cyclin A1, and CDK2 were downregulated, and Bax expression was upregulated by overexpression of RSK4 in gastric cancer cells, which is consistent with the results of our study." (PMID 36031631, 2022).
hepatocellular carcinoma (7 papers, 2013 to 2024). A malignant tumor that arises from hepatocytes. "“MicroRNA-1271 functions as a potential tumor suppressor in hepatitis B virus-associated hepatocellular carcinoma through the AMPK signaling pathway by binding to CCNA1” published in Journal of cellular physiology was retracted due to duplication of image and paper mill." (PMID 38984306, 2024). "In order to confirm the cell cycle arrest of curcumin on hepatocellular carcinoma cells, the cancer cells treated with curcumin were analyzed by flow cytometry and immunostaining of cyclin A1 and cyclin B1." (PMID 37333486, 2023). "It seemed that curcumin could suppress hepatocellular carcinoma cell proliferation via downregulating the expression of cyclin A1." (PMID 37333486, 2023). "It seemed that curcumin could inhibit hepatocellular carcinoma cell proliferation by downregulating the expression of cyclin A1." (PMID 37333486, 2023).
lung carcinoma (6 papers, 2013 to 2024). "Elevated levels of CCNA1 cause chromatin condensation and apoptosis in renal, ovarian and lung carcinoma cells." (PMID 36834539, 2023). "Elevated cyclin A1 levels lead to chromatin condensation and apoptosis in renal, ovarian and lung carcinoma cells." (PMID 24019929, 2013). "EPIC1 downregulation decrease the expression of Cyclin A1, Cdc20, and Cdc45 in lung cancer cells." (PMID 32322669, 2020). "In lung cancer, SETD7 can inhibit cell proliferation by downregulating cyclins (CCNA1 and CCND1)." (PMID 39522095, 2024). "The previous study of PRR11 was conducted and interpreted in the setting of lung cancer and showed that PRR11-knockdown dysregulated the expression of multiple important gene in critical pathways such as cell cycle, tumorigenesis and metastasis (e.g. CCNA1, RRM1, MAP4K4 and EPB41L3)." (PMID 26252227, 2015).
glioma (5 papers, 2012 to 2022). A benign or malignant brain and spinal cord tumor that arises from glial cells (astrocytes, oligodendrocytes, ependymal cells). "Among cell cycle regulators, IDHwt gliomas were significantly more likely to have CDK1 loss and less likely to have cyclin A1 gene loss or cyclin D1 or E2 gene gain." (PMID 26091668, 2015). "In exploring the molecular mechanism of LATS1 tumor-suppressing function in glioma, we found that restoration of LATS1 expression significantly inhibited expression of cell cycle factor CCNA1 in glioma U251 cells." (PMID 22909338, 2012). "Consistent with this presumption, we found that overexpression of LATS1 significantly reduced the expression of CCNA1 by western blot assay in glioma U251 cells." (PMID 22909338, 2012). "We speculated CCNA1 might be involved in the cell cycle regulation pathway of LATS1 in glioma." (PMID 22909338, 2012). "And CCNA1, DTL, and SFN were discovered as novel biomarkers for glioma diagnosis, treatment, and prognosis evaluation." (PMID 36092717, 2022). "In summary, CCNA1, DTL, and SFN could serve as a new biomarker for glioma diagnosis, treatment, and prognosis evaluation." (PMID 36092717, 2022).
head and neck squamous cell carcinoma (4 papers, 2012 to 2016). A squamous cell carcinoma that arises from any of the following anatomic sites: lip and oral cavity, nasal cavity, paranasal sinuses, pharynx, larynx, and salivary glands. "Methylation of Cyclin A1 could be related to the presence of HPV16 DNA in Head and Neck Squamous Cell Carcinoma (HNSCC) and Cervical Neoplasia." (PMID 22712549, 2012).
oral cancer (4 papers, 2006 to 2023). "Additionally, AITC downregulated KDM8 and CCNA1 expression while inducing histone H3K36me2 expression in oral cancer cells." (PMID 37893043, 2023). "KDM8 and CCNA1 repression by AITC markedly suppressed oral cancer’s proliferation or growth." (PMID 37893043, 2023). "To further support our observations, we performed Western blotting analysis on various oral cancer cell lines (SAS, SCC25, and HSC3) and human normal gingival fibroblast cells (HGF) to investigate KDM8 and CCNA1 expression." (PMID 37893043, 2023). "Querying the TCGA HNSCC dataset we identified 8 potential mRNA targets (ESM1, KLF4, IL8, CCL20, IL24, CCNA1, TIMP4 and MMP1) from our validated 20 mRNA panel, which were aberrantly expressed in HNSCC and controlled by CELF1 in oral cancer cells." (PMID 26498364, 2015). "As a result, this study utilizes a preclinical PDTX model and an oral cancer cell line to explore whether AITC’s anticancer effects on cell proliferation in oral cancer are modulated through KDM8 and CCNA1." (PMID 37893043, 2023).
bladder cancer (3 papers, 2014 to 2023). "USP2a interacted with cyclin A1 and blocked the ubiquitination of cyclin A1, contributing to cyclin A1 accumulation, which led to promotion of cell proliferation in bladder cancer." (PMID 37215134, 2023). "To analyze samples negative for BCL2 methylation, we expanded the MethyLight-based analysis by six additional promoter CpG islands previously reported to be frequently hypermethylated in bladder cancer, including CCNA1, EOMES, HOXA9, POU4F2, SALL3 and VIM2." (PMID 24732047, 2014).